RNU6-1112P (RNA, U6 small nuclear 1112, pseudogene)
Gene: Small nuclear RNA gene on chromosome 4 (40,077,884 to 40,077,982, forward strand). Ensembl gene ENSG00000200455.
Homologues: Orthologues: chimpanzee U6 (100% identical), macaque U6 (98% identical), pig U6 (73% identical), dog U6 (69% identical), rat LOC120094873 (64% identical). Paralogues in human: RNU6-12P (89% identical), RNU6-13P (89% identical), RNU6-19P (89% identical), RNU6-32P (89% identical), RNU6-1 (88% identical), RNU6-1060P (88% identical), RNU6-1124P (88% identical), RNU6-17P (88% identical), RNU6-18P (88% identical), RNU6-2 (88% identical), RNU6-24P (88% identical), RNU6-31P (88% identical), and 1286 more.